AMOTL1 (angiomotin like 1)
Description:
Inhibits the Wnt/beta-catenin signaling pathway, probably by recruiting CTNNB1 to recycling endosomes and hence preventing its translocation to the nucleus.
Synonyms: JEAP; CFCHS
Tractability: Antibody: its Gene Ontology location is reachable by antibodies, with medium confidence. PROTAC: UniProt records ubiquitination sites on it; ubiquitination databases record sites on it.
Gene: Protein-coding gene on chromosome 11 (94,706,431 to 94,876,748, forward strand). Ensembl gene ENSG00000166025.
Subcellular location: Cell junction, tight junction
Subcellular location (Human Protein Atlas): Cytosol; Cell Junctions
Pathways (Reactome):
Signal Transduction: Signaling by Hippo
Gene Ontology:
Molecular function: identical protein binding; protein binding
Biological process: actin cytoskeleton organization; angiogenesis; establishment of cell polarity involved in ameboidal cell migration; hippo signaling; regulation of cell migration
Cellular component: bicellular tight junction; COP9 signalosome; cytoplasmic vesicle; cytosol; plasma membrane; apical plasma membrane; lamellipodium
Genetic constraint (gnomAD): Loss-of-function variants: 43 observed, 95.41 expected, observed/expected ratio (o/e) 0.45, 90% interval 0.35 to 0.58. The upper end of that interval is the gene's LOEUF score, 0.58, which puts it in group 2 of 6, group 1 being the genes least tolerant of losing a copy. Missense variants: 1,106 observed, 1,229.8 expected, observed/expected ratio (o/e) 0.9, 90% interval 0.86 to 0.94. Synonymous variants: 481 observed, 483.07 expected, observed/expected ratio (o/e) 1, 90% interval 0.92 to 1.07.
Homologues: Orthologues: chimpanzee AMOTL1 (99% identical), macaque AMOTL1 (98% identical), pig AMOTL1 (92% identical), rabbit AMOTL1 (92% identical), guinea pig AMOTL1 (92% identical), dog AMOTL1 (90% identical), rat Amotl1 (89% identical), mouse Amotl1 (88% identical), tropical clawed frog amotl1 (63% identical). Paralogues in human: AMOT (50% identical), AMOTL2 (36% identical).
Diseases named in the same sentence as AMOTL1 in open-access papers:
AMOTL1 is named in the same sentence as 27 diseases in open-access papers, as found by Europe PMC text mining. Sharing a sentence is not in itself a finding about the gene and the disease. The quoted sentences say what the papers report.
breast cancer (13 papers, 2014 to 2023). A primary or metastatic malignant neoplasm involving the breast. "The expression of AMOTL1 and IFRD1 was linked to an increased risk of breast cancer, whereas ARRB1 was associated with a protective effect." (PMID 37644433, 2023). "Among the candidate CpGDMs, we found eight genes with differential methylation previously associated with breast cancer susceptibility and pathology in the G2SBC and COSMIC Databases (AMOTL1, CDCP1, CYFIP1, MAP3K6, MIB2, SDK1, TAL1, and TYROBP)." (PMID 33145876, 2021). "AMOTL1 has been shown to act as an oncogene in breast cancer and cervical cancer, and AMOTL2 has been reported to act as an oncogene in breast cancer and suppressor glioblastoma carcinogenesis." (PMID 31330820, 2019). "We then assessed the role of AmotL1 in two tumor model systems, the transgenic model of breast cancer MMTV-PyMT and the Lewis Lung Carcinoma (LLC) transplanted tumor model." (PMID 27464479, 2016). "We show that AmotL1 is essential for normal establishment of vascular networks in the post-natal mouse retina as well as in a transgenic breast cancer model." (PMID 27464479, 2016). "Moreover, AMOTL1 protein expression also correlates with the progression of breast cancer aggressiveness and metastasis by stimulating Src activity." (PMID 36768425, 2023). "Circ-Amotl1 was highly expressed in breast cancer (BC) tissues and cell lines." (PMID 30999909, 2019). "Here, we identified a circular RNA of angiomotin-like 1 (circAMOTL1) as an important player which may be responsible for the adverse resistance against PAX in breast cancer cells." (PMID 31819016, 2019). "Decreased AMOTL1 expression was observed in breast cancer and cervical cancer." (PMID 29650031, 2018). "Currently, AMOTL1 was mainly reported as oncogene in breast cancer and cervical cancer." (PMID 29650031, 2018). "For example, circ-Amotl1 derived from angiomotin-like 1 (AMOTL1) promotes tumorigenesis by binding to and retaining c-Myc within the nuclei in breast cancer." (PMID 31718709, 2019). "From two pairs of matched breast cancer samples, we found that some of the detected CNVs contained some genes that were related to breast cancer, such as PDZK1, XRCC4, Fbxl17, ITGBL1, RORA, BAGE, AMOTL1, RAP80, PIWIL4, CSE1L, and USP18." (PMID 34262604, 2021). "Even though our preliminary data indicate that DNA vaccination against AmotL1 is not effective in the prevention of mammary tumor appearance in BALB-neuT mice, encouraging data have come from a combined DNA vaccine against HER2 and AmotL1." (PMID 25136593, 2014).
cervical carcinoma (9 papers, 2017 to 2023). A carcinoma arising from either the exocervical squamous epithelium or the endocervical glandular epithelium. "Importantly, upregulation of AMOTL1 mRNA and circAMOTL1 are associated with a poor prognosis in cervical cancer patients." (PMID 36768425, 2023). "circAMOTL1 was found to serve as a competing endogenous RNA to prompt the expression of AMOTL1 through sponging miR-485-5p in cervical cancer." (PMID 35003259, 2021). "circAMOTL1 enhances expression of the parent gene AMOTL1 by sponging miR-485-5p, which promotes cervical cancer progression." (PMID 33234130, 2020). "AMOTL1 expression was upregulated by overexpressing circAMOTL1 in cervical carcinoma cells." (PMID 33344445, 2020). "miR-124 in cervical cancer induced the suppression of the EMT process and decreased migration, invasion, and VM due to its specific interaction with 3′UTR of the angiomotin like 1 (AmotL1) protein that regulates cell migration related to angiomotin." (PMID 31993365, 2019). "Likewise, in cervical cancer cells, a study showed that miR-124 exerts a negative effect on angiomotin-like protein 1 (AmotL1), which regulates the EMT phenotype, leading to vasculogenic network suppression." (PMID 31772665, 2019).
gastric cancer (3 papers, 2020 to 2023). A primary or metastatic malignant neoplasm involving the stomach. "Recent studies demonstrate that AMOTL1, a member of the Angiomotin family, holds oncogenic potentials in glioma, breast, and gastric cancers." (PMID 37558679, 2023). "Specifically, AMOTL1 promotes tumorigenesis via interacting with YAP1, a vital factor of the Hippo pathway, to induce its nuclear accumulation in gastric cancer and glioma." (PMID 37558679, 2023).
prostate carcinoma (3 papers, 2019 to 2023). A carcinoma that arises from epithelial cells of the prostate gland. "circAMOTL1L (circBase ID: hsa_circ_0000350) is derived from back-splicing of the Amotl1 mRNA (from exon-2 to exon-3) and is located on chr11:94,528,176-94,533,477; it has been reported to exhibit a tumor suppressor characteristic in prostate cancer." (PMID 34646428, 2021). "circAMOTL1L, derived from the circularization of the exon-2 and exon-3 of the Amotl1 gene, was reported to exhibit a tumor suppressor characteristic in prostate cancer by modulating the miR-193a-5p/Pcdha axis to suppress the migration and invasion of PCa cells." (PMID 34646428, 2021). "Moreover, a previous report revealed that AmotL1 is critical for cadherin-11-mediated cell migration and may be involved in promoting migration in prostate cancer." (PMID 30531834, 2019).
cardiomyopathy (2 papers, 2019 to 2024). A disease of the heart muscle or myocardium proper. "For instance, the most cited paper reported that circ-Amotl1, a circular RNA, can physically bind with PDK1 and AKT1, thus promoting the protective nuclear translocation of pAKT, which provides protection against Adriamycin-induced cardiomyopathy." (PMID 38680417, 2024).
glioma (2 papers, 2023). A benign or malignant brain and spinal cord tumor that arises from glial cells (astrocytes, oligodendrocytes, ependymal cells). "This study also indicates that AMOTL1 could serve as a diagnostic marker and a potential target for glioma treatment." (PMID 36768425, 2023). "For instance, AMOTL1 protein expression increases in glioma and gastric cancer, where it protects YAP from degradation, which stimulates the expression of proto-oncogenic genes such as connective tissue growth factor (CTGF)." (PMID 36768425, 2023). "In glioma, the inhibition of AMOTL1, both in vitro and in vivo, has an anti-tumor effect." (PMID 36768425, 2023).
breast tumours (1 paper, 2006). "This study examined the expression of angiomotin and its analogues, angiomotin-like 1 (L1) and -like 2 (L2) in breast tumour tissues, and analysed their correlation with angiogenesis and clinical outcomes." (PMID 16430777, 2006). "We examined the expression of angiomotin and its analogue molecules angiomotin-like-1 and like-2 in a cohort of breast tumours against the clinical information." (PMID 16430777, 2006). "Although angiomotin-like-1 and -like-2 proteins are also expressed at higher levels in breast tumour tissues, the difference is not significant." (PMID 16430777, 2006).
cardiac hypertrophy (1 paper, 2022). "AMOTL1 has been associated with the enlargement and proliferation of cardiomyocytes, cardiac hypertrophy, and angiogenesis." (PMID 35588128, 2022).
glomerular disease (1 paper, 2021). "It has been shown to interact with α-actinin-4 as well as angiomotin-like 1 (Amotl1) and seems to be involved in the pathogenesis of glomerular disease due to a regulation of the actin dynamics." (PMID 34879092, 2021).
hepatocellular carcinoma (1 paper, 2017). A malignant tumor that arises from hepatocytes. "Altogether, the present data indicate that XAV-939 and G007-LK Tankyrase inhibitors could suppress proliferation of hepatocellular carcinoma cells and downregulate YAP/TAZ by stabilizing AMOTL1 and AMOTL2 proteins, thus representing new potential anticancer drugs against hepatocellular carcinoma." (PMID 28877210, 2017).
invasive ductal carcinomas (1 paper, 2021). "Previous reports have shown that AMOTL1 is overexpressed in invasive ductal carcinomas, leading to invasive behaviors." (PMID 33707576, 2021).
myocardial infarction (1 paper, 2024). Gross necrosis of the myocardium, as a result of interruption of the blood supply to the area, as in coronary thrombosis. "For instance, circ-Amotl1 has been shown to reduce myocardial apoptosis and ventricular remodeling post-myocardial infarction by promoting AKT protein phosphorylation and nuclear translocation." (PMID 39080192, 2024).
orofacial clefting (1 paper, 2024). "For example, AMOTL1-related orofacial clefting, cardiac anomalies, and tall stature." (PMID 39506859, 2024).
splenic marginal zone lymphoma (1 paper, 2025). Splenic marginal zone lymphoma is a rare, indolent B-cell non-Hodgkin lymphoma characterized by abnormal clonal proliferation of mature B-lymphocytes with involvement in the spleen, bone marrow and, frequently, the blood. "Meanwhile, AMOTL1 has been reported as recurrently mutated in splenic marginal zone lymphoma." (PMID 40320296, 2025).
tumor (11 papers, 2006 to 2026). "This is quite similar to what we have observed in AmotL1 deficiency in endothelial cells during normal and tumor blood vessels development." (PMID 27464479, 2016). "Analysis of the infiltrating blood vessels in the tumor area revealed a marked difference in morphology between the control and AmotL1 deficient mice." (PMID 27464479, 2016). "AMOTL1 appears to be specifically involved in angiogenesis and cancer, potentially acting as a tumour suppressor or an oncogene." (PMID 29391579, 2018). "We studied the role of AmotL1 in normal retinal as well as tumor angiogenesis using inducible endothelial-specific knock-out mice." (PMID 27464479, 2016). "Similar to the transgenic MMTV-PyMT model, ablation of amotL1 in LLC tumor endothelium resulted in a significant increase in vessel diameter." (PMID 27464479, 2016). "Using multivariate analysis of the following factors, nodal status, tumour grade, angiomotin, angiomotin-like-1 and angiomotin-like-2, we have found that nodal status (p = 0.0185) and angiomotin transcript (p = 0.031) were independent survival factors." (PMID 16430777, 2006). "Angiomotin like-1 and like-2 transcript were also high in tumour tissues compared with normal tissues (respectively), however, the difference was not statistically significant." (PMID 16430777, 2006). "Further studies may shed light whether the tumor: endothelial interactions are dependent on mechanical forces relayed by AmotL1." (PMID 27464479, 2016). "Although there was a trend of higher levels of angiomotin-like-1 and -like-2 in node positive tumours, this was not significant (p = 0.08 and p = 0.6, respectively)." (PMID 16430777, 2006). "In these selective paired samples, it was seen that most tumour samples had a stronger angiomotin signal, however, signals for angiomotin-like-1 and -like-2 were not different between normal and tumour tissues." (PMID 16430777, 2006).
cancer (10 papers, 2016 to 2025). A tumor composed of atypical neoplastic, often pleomorphic cells that invade other tissues. "Both products from the AMOTL1 gene have well-known functions in physiology, cancer, and other disorders." (PMID 36768425, 2023). "AMPK phosphorylates angiomotin like 1 (AMOTL1), an adaptor protein in the Hippo-Yap pathway, and thus blocks Yes1 associated transcriptional regulator (YAP) activity, dampening cancer cells proliferation and survival." (PMID 35414794, 2022). "The overexpression of circ-Amotl1 results in cancer progression and metastasis through c-Myc stabilization and retention in the nucleus, with circ-Amotl1 as the decoy molecule." (PMID 32781555, 2020). "AMPK phosphorylates angiomotin like 1 (AMOTL1), an adaptor protein in the Hippo-Yap pathway, and thus blocks Yes1 associated transcriptional regulator (YAP) activity, which impairs cancer cells’ proliferation and survival." (PMID 32807225, 2020). "The AMOTL1 protein plays important roles in regulating cell division, cell junctions, and other cellular functions in physiological and pathological conditions, especially in cancer." (PMID 36768425, 2023). "Silencing circ‐Amotl1 could decrease cancer cell proliferation and increase cell apoptosis." (PMID 33277969, 2022). "AMOTL1, YAP1, and CTGF were silenced, respectively, in GC cell lines followed with the treatment of first-line anti-cancer drugs (Cisplatin and 5-FU)." (PMID 32313226, 2020). "For example, AMOT, AMOTL1, as well as AMOTL2 exert both oncogene or tumor suppressive gene in different cancer types." (PMID 29650031, 2018). "Taken together, the functional roles of AMOT-p80, AMOT-p130, AMOTL1, and AMOTL2 in different cancer types are controversial and they highly depend on cell context." (PMID 29650031, 2018). "Differentially methylated CpGs related to NXPH4 and LBX2 have previously been described in a study that developed a placental epigenetic clock, whereas aberrant methylation and/or expression of NXPH4, EPS8L2, AMOTL1, IRX2, and LBX2 have also been described in multiple types of cancers." (PMID 40338255, 2025). "CircRNAs produced from the Angiomotin-like 1 (AMOTL1) gene provide an example of a variety of functions that this class of molecules could serve in health and disease, particularly in cancer." (PMID 36768425, 2023). "However, unlike AMOTL1 and SDPR, the role of TSHZ2 down-regulation in cancer cells has not been fully elucidated." (PMID 26744317, 2016).
infection (1 paper, 2013). The state of being infected such as from the introduction of a foreign agent such as serum, vaccine, antigenic substance or organism. "As infection continues, at 90DPI, Angiomotin like-1 (component of tight junctions) and other adherens junction proteins such as cadherin 11, 23, catenin alpha 1 and FAK also displayed significantly decreased expression." (PMID 23593167, 2013).
AMOTL1 also shares sentences with these, for which no sentence is quoted: meningioma (2 papers); attention deficit-hyperactivity disorder (1); cardiovascular diseases (1); central neurocytoma (1); head and neck cancer (1); Lewis Lung Carcinoma (1); lung carcinoma (1); metabolic disease (1); nasopharyngeal carcinoma (1); psychiatric disorder (1).